FGFR2 (fibroblast growth factor receptor 2)
Diseases named in the same sentence as FGFR2 in open-access papers (continued):
Sharing a sentence is not in itself a finding about the gene and the disease.
hypospadias (13 papers, 2010 to 2026). Hypospadias is the displacement of the urethral meatus on the ventrum of the penis. "For example, MAFB, FGF10, and FGFR2 are genes critical for urethral closure in both humans and mice, with mutations resulting in severe hypospadias." (PMID 41596366, 2026). "FGFR2, whose mutations were associated with hypospadias, might be coregulated by SFPQ and HNRNPA1." (PMID 32316190, 2020). "While gene variants of FGFR2 may influence the risk of hypospadias in humans, conditional inactivation of FGFR2 in mouse models resulted in blockade of the XY-specific gonad growth and disruption of testis differentiation, leading to a male-to-female sex reversal phenotype." (PMID 21048976, 2010). "Several FGF genes, including FGF8, FGF10, and fibroblast growth factor receptor 2 (FGFR2), were found to be expressed in the foreskin of children with hypospadias." (PMID 40072077, 2025). "The results show decreased expressions of Shh, Bmp4, Fgf8, Fgf10 and Fgfr2 in the genital tubercle in male rats with hypospadias." (PMID 39728417, 2024). "However, FGFR2 is nearly ubiquitously expressed, particularly in the brain, respiratory system, male and female tissues, and skin; thus, mutations in this gene have been associated with other clinical phenotypes, such as Hypospadias and Lacrimo-auriculo-dento-digital syndrome." (PMID 37733178, 2023). "In a murine model, ectodermal deletion of FGFR2 resulted in the most severe hypospadias with major alterations to the foreskin, highlighting a major role of FGFR2 in the developing genital surface epithelia." (PMID 31718599, 2019). "Significant alterations in DNA methylation of sex hormone receptor genes (ESR1 and AR) and fibroblast growth factor (FGFR2 FGF8) may correlate with abnormal expression of these genes in patients with hypospadias." (PMID 39959693, 2025). "Fgf8, Fgf10, and their receptor Fgfr2 were identified as candidate genes for human hypospadias." (PMID 40072077, 2025).
lung squamous cell carcinoma (13 papers, 2013 to 2025). "We sequenced 503 lung squamous cell carcinoma resected from October 2007 to March 2013 for the prevalence of activating FGFR2 and FGFR3 mutations." (PMID 26486077, 2015). "KIAA1967 has been reported as one of the fusion partners with FGFR2 by transcriptome sequencing in lung squamous cell carcinoma of the TCGA database." (PMID 32316112, 2020). "Liao and colleagues reported in 2013 the identification of inhibitor-sensitive oncogenic FGFR2 and FGFR3 mutations in lung squamous cell carcinoma from the Cancer Genome Atlas (TCGA) dataset." (PMID 26486077, 2015). "Results of this study showed that HON has a higher docking score than Phosphomethylphosphonic acid guanylate ester to bind FGFR2; however, HON has been shown to inhibit FGFR signaling in lung squamous cell carcinoma." (PMID 36601474, 2022).
non-small cell lung carcinoma (13 papers, 2020 to 2025). A group of at least three distinct histological types of lung cancer, including non-small cell squamous cell carcinoma, adenocarcinoma, and large cell carcinoma. "While the frequency of FGFR2 mutations is highest in endometrial cancer (10–12%), it is below 5% in, e.g., non-small-cell lung cancer (NSCLC), gastric and urothelial cancer." (PMID 36231142, 2022). "With the exception of NTRK and RET fusions, all of the US FDA approvals are tumor-specific: ALK (non-small cell lung cancer [NSCLC]), ROS1 (NSCLC), and FGFR2-3 (urothelial, cholangiocarcinoma)." (PMID 37853341, 2023).
thyroid cancer (13 papers, 2009 to 2025). "The anti FGFR2 antibody led to the identification of a sperm band of approximately 125 kDa, similar to that reported in human thyroid carcinoma cells." (PMID 25970615, 2015). "In particular, FGFR2 is the only member of FGFRs family to be consistently expressed in normal human thyroid tissue and strongly down-modulated in thyroid cancer." (PMID 24899248, 2014). "Other functional studies reinforced these differences between MAGE expressions in thyroid lesions, suggesting that MAGE A3/6 and FGFR2-IIIb participate in the development of thyroid cancer." (PMID 25825704, 2014). "FGFR-2 down-modulation in thyroid cancer has been justified as a result of DNA promoter methylation of FGFR-2 gene." (PMID 23977259, 2013). "The subsequent FGFR-2 re-expression seemed to reduce thyroid cancer progression by enhancing apoptosis in tumoral cells." (PMID 23977259, 2013). "The aim of this study was the evaluation of a possible correlation between FGFR-2 expression and the pathological progression from normal thyroid tissue to thyroid carcinoma." (PMID 23977259, 2013). "Although we did not measure the association between FGFR2 methylation and gene expression due to lack of RNA samples, another study of thyroid cancer documented an inverse correlation between the DNA methylation of 5′UTR region at FGFR2 and gene expression." (PMID 29588807, 2018). "In thyroid cancer, FGFR2 expression is controlled by methylation of the DNA promoter." (PMID 26933914, 2016). "It has been previously demonstrated a significant FGFR2 down-modulation in thyroid cancer." (PMID 24899248, 2014). "Such decrease suggests that FGFR-2 down-modulation may be a critical step in thyroid cancer progression, and it can be assumed that FGFR-2 alteration may be an early event in the development of thyroid neoplasia." (PMID 23977259, 2013). "Furthermore, we suggest the potential use of FGFR-2 as an early marker for thyroid cancer diagnosis." (PMID 23977259, 2013). "This analysis confirmed both KGFR and FGFR2-IIIc down-modulation (0.3-fold and 0.2-fold, respectively, p < 0.01) in thyroid carcinomas." (PMID 24899248, 2014). "FGFR-2 is the only FGFR that is consistently expressed in normal thyroid tissue, whereas it appears to be reduced in thyroid cancers." (PMID 23977259, 2013). "FGFR2 was generally downregulated in most of the tumors, including COAD, kidney renal clear cell carcinoma (KIRC), LUAD, prostate adenocarcinoma (PRAD), and thyroid carcinoma (THCA)." (PMID 32596330, 2020). "In addition, transfection of FGFR2 into the FGFR2−/low CD44low MKN45 GC cell line resulted in increased CD44 and thyroid cancer protein (TC1), a downstream gene of FGFR2." (PMID 27107424, 2016). "In thyroid cancer it has been observed a FGFR-2 down-modulation, but the role of this receptor has not been yet clarified." (PMID 23977259, 2013).
pulmonary fibrosis (12 papers, 2013 to 2025). Chronic progressive interstitial lung disorder characterized by the replacement of the lung tissue by connective tissue, leading to progressive dyspnea, respiratory failure, or right heart failure. "They identified Regulated IRE1-Dependent Decay (RIDD) as a key effector of IRE1α signaling that drives differentiation of alveolar epithelial type 2 cells to damage-associated intermediate cells and contributes to pulmonary fibrosis, likely by degrading Fgfr2 mRNA." (PMID 41090359, 2025). "Of these six master regulators, three master regulators are found to be associated with pulmonary fibrosis (ERBB2, EGFR and FGFR2) and one with inflammation (FYN)." (PMID 37206915, 2023). "For example, using the bleomycin-induced lung fibrosis model, it was reported that mice with specific deletion of Fgfr2 in SFTPC-positive AT2 cells were less able to repair after injury, showed increased mortality, and had fewer AT2 cells overall." (PMID 36445537, 2022). "Our findings suggest that TGF-β/Smad signaling contributes to the development of EMT by regulating FGFR2 IIIc alternative splicing in BLM-induced lung fibrosis." (PMID 30049844, 2018). "Herein, we aimed to explore the underlying mechanisms of lung fibrosis mediated by EMT, with a focus on the alternative splicing of fibroblast growth factor receptor 2 (FGFR2), using bleomycin (BLM)-induced lung fibrotic and transgenic mouse models." (PMID 30049844, 2018). "Thus, the goal of the present study is to explore the underlying mechanisms of EMT-mediated lung fibrosis using BLM-induced lung fibrotic and transgenic mouse models, with a focus on the alternative splicing of FGFR2." (PMID 30049844, 2018). "These genes were identified in reports of the alternative splicing in pulmonary fibrosis of known etiologies CD44, RXFP1, and CD146, a pulmonary fibrosis mouse model (FGFR2), and a genetic link between COVID-19 and IPF (DP99 and ATP11A)." (PMID 39937013, 2025). "The expression of FGF2/FGFR2 axis is elevated in IPF samples, and FGFR2-dependent signaling is involved in pulmonary fibrosis." (PMID 34276664, 2021). "In the present study, our findings have shown an increased level of TGF-β during BLM-induced lung fibrosis and BLM-induced alternative splicing of FGFR2." (PMID 30049844, 2018). "While expression of genes coding for soluble mediators (e.g. cytokines) were unchanged, receptors for several mediators known to participate in lung fibrosis were up-regulated (CCR2, FGFR2, FLT1, IGF1R, IL1R1 and IL6R)." (PMID 23844029, 2013). "In addition, our previous study shows that BLM inhibited ESRP1 expression, resulting in enhanced alternative splicing of FGFR2 to the mesenchymal isoform IIIc, thereby induces EMT in the lung fibrosis." (PMID 31868203, 2020).
ameloblastoma (11 papers, 2013 to 2026). The most common odontogenic tumor, arising from the epithelial component of the embryonic tooth and usually affecting the molar-ramus region of the mandible or maxilla. "Associations with other mutations, such as SMO and FGFR2, have also been reported in maxillary ameloblastomas." (PMID 38021761, 2023). "Other than the BRAF gene in the MAPK pathway, FGFR2 and RAS mutations were also part of the pathogenesis of most ameloblastoma cases." (PMID 36428683, 2022). "Mutations in FGFR2 have been described in 4/28 (14%), 3/50 (6%), and 2/39 (5%) of BRAF wild-type conventional ameloblastomas." (PMID 35048058, 2021). "In a similar way, other somatic mutations have been reported in ameloblastoma, mainly affecting: SMO, other MAPK pathway-related genes such as KRAS, NRAS, HRAS, FGFR2 and in a lower frequency, PTEN and CTNNB1 among others." (PMID 35048068, 2021). "Mutually exclusive and less common mutations affecting other MAPK-related genes, such as KRAS, NRAS, HRAS, and FGFR2 (a receptor whose stimulation activates MAPK/ERK pathway) have been reported in BRAF wild-type ameloblastomas." (PMID 35048058, 2021). "FGFR1 was expressed in the tumor and stromal cells of ameloblastoma, the expression of FGFR2 was investigated only in the tumor cells." (PMID 24002438, 2013). "In maxillary ameloblastomas, additional mutations included BRAF L597R, FGFR2, PIK3CA, and SMO." (PMID 38021761, 2023). "However, other Authors showed additional mutations to B-Raf in ameloblastomas, such as NRAS, HRAS, KRAS, FGFR2, and PIK3CA,10,23,44 suggesting they may represent secondary mutations occurring later in the pathogenesis of ameloblastoma." (PMID 35468886, 2022). "At the molecular level, mutations in the mitogen-activated protein kinase (MAPK) pathway, including BRAF V600E, FGFR2, and NRAS, have been identified in ameloblastomas, including PA." (PMID 41030734, 2025). "Next, we performed immunohistochemistry to analyze the expression of FGFR1 and FGFR2, the specific receptors of FGF7 and FGF10, in the ameloblastoma specimens and in AM-1 cells." (PMID 24002438, 2013). "We examined 32 cases of ameloblastoma as well as AM-1 cells (an ameloblastoma cell line) and studied the expression of FGF3, FGF7, FGF10 and their specific receptors, namely, FGF receptor (FGFR) 1 and FGFR2." (PMID 24002438, 2013). "The expression of FGF7, FGF10, FGFR1 and FGFR2 was detected in ameloblastoma cells and AM-1 cells, while that of FGF3 was not." (PMID 24002438, 2013). "The expression of FGF1, FGF2, FGFR2 and FGFR3 in ameloblastoma was previously reported and it was concluded that FGF1 and FGF2 may contribute to the growth and development of ameloblastoma mediated by their receptors." (PMID 24002438, 2013).
osteosarcoma (11 papers, 2014 to 2024). A usually aggressive malignant bone-forming mesenchymal neoplasm, predominantly affecting adolescents and young adults. "A recent study of somatic sequence and structural mutations in canine osteosarcoma showed that focal amplifications spanning FGFR2 are the most common of any oncogene." (PMID 30890123, 2019). "Conversely, ALT‐negative tumors were particularly enriched in genes related to the FGFR2‐associated signaling pathways that may be associated with telomerase reactivation in pediatric osteosarcoma." (PMID 35920001, 2022). "Given that FGFR2 downregulation is significantly associated with both poor overall survival and event-free survival in our data, FGFR2 disruption may serve to inhibit differentiation in osteosarcoma." (PMID 35887382, 2022). "FGFR2 expression was found to be reduced in osteosarcoma mouse models, but the mechanism by which FGFR2 is downregulated remains elusive." (PMID 35887382, 2022). "Pazopanib molecular targets (c-KIT-CD117, FGFR2-3 PDGFRα-β, VEGFR-1-2, and -3) displayed a plasma membrane heterogeneous degree of expression in seven osteosarcoma cell lines, with FGFR2, VEGFR3, and PDGFRβ represented most." (PMID 32531992, 2020). "Interestingly, researchers found miR‐671‐5p and miR‐381‐3p can target FGFR2 to suppress cancer by blocking proliferation and progression in osteosarcoma and esophageal squamous cell carcinoma." (PMID 38577722, 2024). "Taken together, we revealed for the first time that Noggin enhances phosphorylation of FGFR2 in both adipose-derived stem cells and osteosarcoma-derived osteoblastic cells and activates FGFR2/Src/Akt and ERK intracellular signaling pathway in adipose-derived stem cells." (PMID 38509118, 2024). "Other examples include miR-133b direct downregulation of FGFR1 expression and RAS-MAPK/PI3K-AKT signaling in osteosarcoma cells, miR-889-3p decreasing FGFR2 expression in cervical cancer and miR-24-3p downregulation of FGFR3 expression in multiple myeloma (MM) and lung adenocarcinoma." (PMID 34068954, 2021). "The FGFR1 and FGFR2 KGDs suggested that osteosarcoma models might be especially sensitive to small molecule FGFR inhibitors." (PMID 26947069, 2016). "Besides, Noggin can specifically activate FGFR2 in osteosarcoma cells." (PMID 38509118, 2024). "Regarding osteosarcoma, a study revealed low expression of FGFR-2 and FGFR-3 across standard and patient-derived osteosarcoma cells." (PMID 32984034, 2020). "Osteosarcomas were significantly enriched for a cluster of six skeletal-pathway kinases that includes FGFR1 and FGFR2." (PMID 30890123, 2019). "In addition, we were able to identify and validate the prognostic significance of FGFR2 and FIBIN expression in predicting osteosarcoma outcome." (PMID 35887382, 2022). "Taken together, these results suggested that FGFR inhibitors might show some utility in osteosarcoma, but that factors in addition to FGFR1 and FGFR2 amplification might explain drug sensitivity in this setting." (PMID 26947069, 2016). "This osteosarcoma selective effect was independent of FGFR1 or FGFR2 amplification status and was also apparent when FGFR1 or FGFR2 amplified tumor cell lines were excluded from the analysis (AZD4572, p = 7.2 × 10−3 and PD173074, p = 4.3 × 10−2)." (PMID 26947069, 2016).
achondroplasia (10 papers, 2010 to 2023). Achondroplasia is the most common form of chondrodysplasia, characterized by rhizomelia, exaggerated lumbar lordosis, brachydactyly, and macrocephaly with frontal bossing and midface hypoplasia. "Although mutations at FGFR2 c.755 are a representative model for selfish mutations in general, further studies will be required to confirm the findings in other genes such as FGFR3 (associated with achondroplasia and thanatophoric dysplasia) and HRAS (associated with Costello syndrome)." (PMID 31348830, 2019).
metastatic disease (10 papers, 2014 to 2024). "Furthermore, we identified a posttreatment secondary kinase mutation in FGFR2, present in a single metastatic tumor sample demonstrating the significance of intertumor heterogeneity within the same patient." (PMID 31371345, 2019). "FGFR2 overexpression and FGF3,4,19 gene amplification were seen in primary tumors but not in our series of metastases indicating that these changes play probably a minor role in metastatic disease." (PMID 30181810, 2018). "This independent analysis again confirmed that the FGFR2 locus was not amplified in a separate region of the metastatic tumor." (PMID 25315765, 2014). "However, the patient’s metastatic recurrence did not harbor this same FGFR2 amplification, suggesting that treatment with a therapeutic small molecule inhibitor may not have had a discernible biological effect on the patient’s metastatic disease." (PMID 25315765, 2014).